OR4A16 (olfactory receptor family 4 subfamily A member 16)
Description:
Odorant receptor.
Synonyms: OR4A16Q; OR11-117
Tractability: Small molecule: it belongs to a druggable protein family. Antibody: UniProt places it where antibodies can reach, with medium confidence; UniProt predicts a signal peptide or a membrane-spanning region; its Gene Ontology location is reachable by antibodies, with medium confidence.
Gene: Protein-coding gene on chromosome 11 (55,343,201 to 55,344,187, forward strand). Ensembl gene ENSG00000181961.
Subcellular location: Cell membrane
Pathways (Reactome):
Sensory Perception: Expression and translocation of olfactory receptors
Gene Ontology:
Molecular function: olfactory receptor activity; G protein-coupled receptor activity
Biological process: detection of chemical stimulus involved in sensory perception of smell; G protein-coupled receptor signaling pathway
Cellular component: plasma membrane; membrane
Genetic constraint (gnomAD): Missense variants: 591 observed, 393.57 expected, observed/expected ratio (o/e) 1.5, 90% interval 1.4 to 1.61. Synonymous variants: 206 observed, 137.19 expected, observed/expected ratio (o/e) 1.5, 90% interval 1.34 to 1.68.
Homologues: Orthologues: chimpanzee OR4A16 (88% identical), mouse Or4a68 (69% identical), rat Or4a68 (68% identical), rat Or4a69 (68% identical), mouse Or4a69 (67% identical), mouse Or4a74 (67% identical), rat Or4a77e (66% identical), mouse Or4a72 (66% identical), mouse Or4a77 (66% identical), mouse Or4a81 (66% identical), mouse Or4a79 (65% identical), rat Or4a72 (65% identical), and 9 more. Paralogues in human: OR4A5 (67% identical), OR4A8 (66% identical), OR4A47 (59% identical), OR4A15 (58% identical), OR4C3 (52% identical), OR4C46 (52% identical), OR4C13 (51% identical), OR4C15 (51% identical), OR4C5 (50% identical), OR4C6 (49% identical), OR4C11 (49% identical), OR4C12 (49% identical), and 116 more.
Diseases named in the same sentence as OR4A16 in open-access papers:
OR4A16 is named in the same sentence as 1 disease in open-access papers, as found by Europe PMC text mining. Sharing a sentence is not in itself a finding about the gene and the disease.
OR4A16 shares sentences with these, for which no sentence is quoted: pancreatic cancer (2 papers).